SOX2 (SRY-box transcription factor 2)
Diseases named in the same sentence as SOX2 in open-access papers (continued):
Sharing a sentence is not in itself a finding about the gene and the disease.
tumor (continued). "Our findings by integrating cellular experiments in vitro, tumor-forming assay in xenograft animal model as well as bioinformatics data mining provide evidence that TAZ enhances CSCs self-renewal and maintenance by direct transcriptional activation of SOX2 in HNSCC." (PMID 31399556, 2019). "Not all Sox2+ cells were tumor-derived, as glial cells in normal P7 cerebellum also expressed Sox2." (PMID 31863004, 2019). "Similarly, in GH-secreting tumor tissues, no co-expression of GH with SOX2, OCT4, or Nestin was observed." (PMID 31708878, 2019). "Here, we have combined genetic and molecular approaches to reveal that deregulation of the pathway can promote and maintain the SOX2+ PSC fate under physiological conditions and that major disruption of this axis transforms SOX2+ PSCs into cancer-initiating cells giving rise to aggressive tumours." (PMID 30912742, 2019). "Notably, treatment of MPM spheroids with 0.1 or 0.5 μM BI 853520 did not change the expression of the putative tumor stem cell markers SOX2, Nanog, CD44, ALDH1, c-myc, and Oct4." (PMID 30539198, 2019). "PSPC1 enhances epithelial–mesenchymal transition (EMT), stemness and tumor growth through the activation of core transcription factors (TFs), such as EMT-TFs (e.g., Snail, Slug, and Twist), cancer stem-like cells (CSC)-TFs (e.g., Oct4, Nanog, and Sox2), and c-Myc4." (PMID 31844057, 2019). "SOX2+ pituitary stem cells are the cell-of-origin of tumours generated in the absence of Lats1." (PMID 30912742, 2019). "A recent study showed that SOX2 overexpression was found in a proportion of women with BRCA1 and BRCA2 mutations who underwent prophylactic salpingo-oophorectomy, and in the majority of patients with HGSOCs, irrespective of tumor stage." (PMID 31850198, 2019). "SOX2 is not expressed in normal skin, but it appears at an early stage in tumour formation." (PMID 29506506, 2018). "Nuclear Ki67 expression in tumor cells was increased in SOX2 negative samples." (PMID 29596469, 2018). "To investigate if BCL11A is required for SOX2-mediated oncogenesis we introduced a doxycycline inducible BCL11A overexpression vector into SOX2-KD cell lines and found that BCL11A overexpression partially rescues the colony and tumour formation abilities of SOX2-KD cells." (PMID 30127402, 2018). "The tumor with the highest SOX2 expression showed almost no ki67 expression." (PMID 29596469, 2018). "Stratification of patients within the TCGA cohort according to tumor size disclosed higher expression of EpCAM expression in bigger tumors (T-classification 3–4 versus 1–2) (Mann-Whitney p-value = 0.013), whereas Sox2 and vimentin expression did not correlate with tumor size." (PMID 30275505, 2018). "SOX2, vimentin and E-cadherin expression was assessed by immunohistochemical staining on serial sections from formalin fixed and paraffin embedded tissue samples of a patient cohort (n = 45) with primary ACC and correlated with patient and tumor characteristics as well as survival." (PMID 29596469, 2018). "Moreover, the expression of both BCL11A and SOX2 was significantly higher in LUSC but not in LUAD tumour samples compared to patient matched normal samples supporting a driver role for these transcription factors in LUSC pathology." (PMID 30127402, 2018). "Our finding might seem contradictory to the stemness role these pluripotent transcription factors play; however, it is worth to emphasize that the mechanistic functions of SOX2, OCT4, and NANOG in cancer cells are a little different in each stage of tumor progress." (PMID 29849920, 2018). "With regard to pCP, we could not detect any antigen reaction for Sox2 in cells of the tumour surrounding CNS tissue." (PMID 29158570, 2017).
tumor (continued). "We found that cells with tumor morphology co-expressed TfR1 and GFAP; additionally we observed co-expression of TfR1 and the stem cell-related markers CD133 and nestin, which is consistent with recently reported data demonstrating that GBM cells co-express TfR1 and the stem cell-related marker SOX2." (PMID 28837569, 2017). "The concern was basically excluded, since YAP or YAPdeltaC even at high expression levels did not induce tumor-like foci or did not increase the number of cells positive for Ki67 (a tumor marker) and Sox2 (a de-differentiation marker), as revealed by immunohistochemistry or western blot analysis." (PMID 29192206, 2017). "The secretion of leptin by adipocytes activates the STAT3 signaling in CSCs and induces the expression of OCT-4 and SOX-2, in turn stimulating the expression of leptin receptor, which maintains a self-reinforcing signaling cascade to expand the CSC population and promote tumor growth." (PMID 28337221, 2017). "Of the most significantly differential enrichment on H3K4me3 and/or H3K27ac marks between SCC and ADC tumours, we found much higher load of H3K27ac and H3K4me3 marks in the SCC tumour compared to the ADC tumour on the squamous genes Sox2, ΔNp63, Ngfr and Krt5/6." (PMID 28387316, 2017). "Consequently, SOX2 was silenced in mammospheres, formed from human tumor tissues which resulted in down regulation of OCT4, NANOG, ALDH1A1, and most importantly, ABCG2 expression (p < 0.01), confirming a direct correlation of SOX2 with ABCG2." (PMID 28835684, 2017). "However, data about the expression of Sox2 and Sox9 in the tumour surrounding brain tissue is lacking." (PMID 29158570, 2017). "However, the Sox2+ cells were obviously not localised within nodular whorls as was described for aCP reminiscent tumours in mouse models." (PMID 29158570, 2017). "However, our results suggested that knocking down Sox2 alone was not enough to significantly inhibit A549 tumor growth in vivo." (PMID 27371094, 2016). "In other words, mutated SOX2+ cells are not transformed into CSCs by oncogenic β‐catenin; mutated SOX2+ PSCs generate cell clusters that have the capacity to induce tumors in a paracrine fashion so that the tumor cells are not derived from SOX2+ cells 34 (paracrine paradigm)." (PMID 26763580, 2016). "The magnitude of SOX2 overexpression was not significantly influenced by tumor stage (early versus late) or by whether or not the patient had chemotherapy prior to surgical excision (data not shown)." (PMID 27492892, 2016). "In addition, SOX2 inhibition slows lung SCC growth and may therefore lead to tumor resistance to chemotherapy that targets rapidly dividing cells." (PMID 26846300, 2016). "Moreover, iHepL and tumor cells do not contain the transgenes for Oct4 and Sox2 in their genomic DNA, confirming the lack of exogenous expression." (PMID 27460218, 2016). "The recent description of Sox2+ murine pituitary stem cells with the potential for multi-lineage differentiation and tumor propagation has offered valuable insight into non-cell-autonomous regulators of tumor growth since resulting tumors were devoid of Sox2 expression." (PMID 27894339, 2016). "Interestingly, “proliferation of tumor cells”, is one of the most repeated subcategories for which IPA analysis assigned an activation Z score close to -2, predicting it ́s inhibition, which is in line with a putative role of SOX2 in cell proliferation." (PMID 27669421, 2016). "Paradoxically, SOX2 expression in tumor cells was almost absent." (PMID 27492892, 2016).
tumor (continued). "Comparison of tumor tissue with non-tumorous tissue obtained from the same patients confirmed that tumor tissues had significantly higher odds of acquiring a copy number alteration in the SOX2 gene." (PMID 26780934, 2016). "No expression of CTNNB1, CTLA4, EPCAM, ERBB2, MET, p40, PD-L1 and SOX2 could be detected in any of the tumors, PD-L1 was negative in tumor as well as stromal cells." (PMID 26943575, 2016). "Our data indicates the possibility that different isoforms or modified versions of SOX2 and NANOG may exist within different GBM tumors, and that a particular isoform present may influence tumor growth and tumor aggression in specific ways, although this remains a topic for further study." (PMID 27617262, 2016). "While we cannot exclude that a tumour might arise from the few proliferative cells that persist to later ages, proliferation data favour an origin for DIPG during the single, early-childhood proliferative peak, from Sox2+Olig2+ progenitors." (PMID 27188978, 2016). "Thus, 10 cases of carcinoma metastasis with uniformly Sox2-immunopositive nuclei for which double-labeling for Sox2 and a tumor-specific marker was not performed were used for Sox2/GFAP double-labeling." (PMID 25713758, 2015). "Furthermore, CD133 depletion suppresses tumor cell proliferation, colony formation, and the expression of core stemness transcription factors including NANOG, octamer-binding transcription factor 4 (OCT4), SOX2, and c-MYC." (PMID 26539911, 2015). "Furthermore, in accordance with the heterogeneity of SNAI2 expression in the primary PCa, the strength of the staining of both SOX2 and NOTCH1 was frequently distinct or strong in the tumor cell clusters forming the expansion/invasion front of high-grade PCa foci." (PMID 25686823, 2015). "However, our results show that patients without this risk factor, and thus not treated, present a strikingly worse outcome when the tumor presents with a SOX2+/CDX2- molecular profile." (PMID 25300947, 2014). "As increased SOX2 expression is seen in tumor, but not adjacent normal tissue, we supposed that elevated SOX2 expression may be related to ACC." (PMID 24828201, 2014). "The mechanisms by which Sox2 regulate tumor invasiveness have not been extensively studied." (PMID 23815808, 2013). "Here, we provide evidence showing that expression of Sox2 in cancer cells induces autophagy of cancer cells by up-regulating ATG10 gene expression and inducing cellular senescence, resulting in reduced malignancy of cancer cells and inhibition of tumor growth ex vivo and in vivo." (PMID 23451179, 2013). "This could be explained by clonal heterogeneity in this individual tumor with additional genetic events strongly driving metastasis in a SOX2-negative population." (PMID 23544055, 2013). "Neither Sox2 nor Oct4 expression was correlated to age, sex, tumor location and pathological type." (PMID 22837720, 2012). "Of note, the selection of tumour initiating cells by this in vivo assay resulted in enrichment of these stem cell markers, over baseline levels in vitro, where differences were 11-fold, 80-fold, 44-fold and 140-fold for ABCG2, Nanog, Notch1 and SOX2 expression, respectively (p<0.05)." (PMID 23226356, 2012). "It is thus possible that the transcription of other oncogenes may not be affected or could even be unregulated by SOX2 and this may be the key reason leading to tumor occurrence in NOD/SCID mice." (PMID 22615765, 2012).
tumor (continued). "Rather, it strongly suggests that SOX2 levels in these tumors are unlikely to rise in isolation, but must be accompanied by other changes in gene expression that work in cooperation with SOX2 to enhance the growth of tumor cells." (PMID 22937156, 2012). "Moreover, neither Sox2 nor Oct4 expression was correlated to age, sex, tumor location, or histological type of the cancers." (PMID 22837720, 2012). "As expected from our observation of a missing association between SOX2 antigen expression and the number of BM-infiltrating plasma cells, we did not observe a correlation between the presence of anti-SOX2 antibodies and the tumor load in the respective patient." (PMID 22190969, 2011). "Importantly, siRNA-mediated knockdown of SOX2 in CSCs significantly suppresses tumour growth and experimental pulmonary metastases of D121 non-small cell lung tumour cells transplanted into syngeneic C57/BL6 mice." (PMID 21468047, 2011). "First, anti-SOX2 immune responses might indeed have an (positive or negative) effect on tumor progression." (PMID 22190969, 2011). "Although Sox2 is inducibly overexpressed in Scgb1a1-expressing cells, Scgb1a1 expression gradually decreases over time, eventually becoming completely absent at late stages of tumor development." (PMID 20548776, 2010). "Other structures of the tumour, like blood vessels, were negative for SOX2." (PMID 17375044, 2007). "Consequently, tumor cells displayed solitary cilia and lack of AQP1 expression, indicating similar defects in multiciliation and epithelial maturation in Sox2-deficient tumor cells." (PMID 40128799, 2025). "Interestingly, the recoveries of HeLa and A549 cells from anti-cancer drug treatments, were accompanied by enhanced expression of the stem cell markers ALDH1, Sox2 and Nanog, which suggests a possible relationship between non-mitotic division and cancer stem cells in tumor recurrence." (PMID 38341593, 2024). "These cells, known as cancer stem cells (CSC) or tumor initiating cells, possibly originate from non-malignant stem cells or progenitor cells, with which they share several characteristics, including the expression of stem cell markers such as SOX2, NANOG, CD133, and CD44." (PMID 38303021, 2024). "However, we find that SOX2 is not highly expressed at late state, indicating that tumor cells along this trajectory might not have survival advantage and regain sensitivity to TKI treatments." (PMID 39687207, 2024). "Given that we found the pluripotency factors NANOG, SOX2, and OCT4 as potential regulators of mesenchymal plasticity, we next aimed to investigate whether their expression predicts clinical variables that relate to therapy resistance and increased tumor cell mobility in EAC." (PMID 38760583, 2024). "The tumor line, SK-N-BE, cells and the human neural progenitor cells (drNPC) predominantly maintained their multi-potency after irradiation, as testified by a high fraction of SOX2-positive cells and by the absent expression of the marker for mature neurons, MAP2b." (PMID 37047534, 2023). "Interestingly, bio-informatic analysis performed by us in the current study revealed a positive and significant correlation between CTH and SOX2 mRNA expression in human GBM tumors but whether this correlation is driven by the tumor microenvironment, or the tumor cells alone remained unknown." (PMID 37300955, 2023). "However, this does not mean that SOX2 levels do not rise during tumor progression." (PMID 35454854, 2022). "Thus, it is important to know that SOX2 positivity does not imply neoplasm." (PMID 35055392, 2022). "Thus, we examined expression of SOX2, a pluripotency marker used to identify tumor cells with stem‐like behavior, as well as KI67 expression and EdU incorporation, which collectively provide information regarding the cycling or proliferative state of the tumor cells." (PMID 36109186, 2022).
tumor (continued). "Based on our data demonstrating a role for STAT3 in regulating the Sox2 expression marker for the cancer stem cell population of Shh MB, we performed an in vivo study to determine whether inhibition of STAT3, prior to established tumor development, affects initiation and formation of Shh MB." (PMID 34482626, 2022). "In addition, Sex-determining region Y-related high-mobility group box 2 (SOX2) was found to occupy the cGAS promoter and repress its transcription, then dampen cGAS/STING signaling and ultimately inhibit ionizing radiation-induced anti-tumor immune responses in NSCLC45." (PMID 35978045, 2022). "However, SOX2+ lineage tracing revealed that the tumor proper did not directly derive from the SOX2+ stem cells, which, on the other hand, were characterized to produce several factors that could fuel tumor development and growth from the neighboring cells." (PMID 33584539, 2020). "Importantly, based on this system, we developed a valuable tool for the selective elimination of SOX2/OCT4-overexpressing CSCs, which facilitates the interrogation of their specific roles in cancer initiation and progression, and the response to therapies in a native tumor microenvironment." (PMID 31500347, 2019). "Additionally, immunohistochemical analysis of GBM tumor tissues demonstrated that only a few integrin α10β1-expressing GBM cells (between 0‒10% in different patient samples) were co-expressed with Nestin, and even fewer of the integrin α10β1-expressing GBM cells were co-expressed with Sox2." (PMID 31027305, 2019). "Thus, it appears that patients with high Sox2 protein expression in the tumor may not suitable for gemcitabine treatment." (PMID 30382189, 2019). "However, in HNACC SOX2 levels were neither correlated with vimentin nor with E-cadherin expression, further supporting a context dependent regulation and function of SOX2 in distinct tumor entities." (PMID 29596469, 2018). "Furthermore, over-expression of SOX2, OCT4 or NANOG alone is sufficient to enhance tumorigenesis in a mouse model; up-regulation of c-MYC has been reported to increase the CSC fraction by 150-fold, enabling tumor formation and serial propagation with as few as 500 cells." (PMID 26506421, 2016). "Targeting pluripotency transcription factors, SOX2, OCT4, and Nanog homeobox, demonstrates promising therapeutic potential that if applied in isolation or together with current treatments may improve overall survival, reduce tumor relapse, and achieve a cure for these patients." (PMID 26258069, 2015). "Thus, we hypothesized that Class III β-tubulin, Sox2, and nuclear Survivin may be used to predict chemoresistance, but not the intrinsic tumor aggressiveness and OS." (PMID 26198101, 2015). "However, 102 of the Sox2 negative cells could not form any tumor in the first transplantation experiment." (PMID 24489842, 2014). "However, no studies exist today of SOX2 expression in tumor metastases." (PMID 25010701, 2014). "However, we could not detect a significant correlation between SOX2 protein expression levels and tumor recurrence." (PMID 23544055, 2013). "The levels of ‘stemness’ associated genes, such as CD133, Sox2, Oct4, Lgr5, Bmi1, and C-myc, were significantly decreased in shRNA-Ascl2/HT-29 and shRNA-Ascl2/LS174T cells in vitro as well as in the corresponding tumor xenograft (CD133 was not performed in shRNA-Ascl2/LS174T cells)." (PMID 22384170, 2012). "From the immunohistochemistry stain of tumor tissues, the possibility that the tumor formed from “escaper” cells that not responsive to shRNA-SOX2 could be excluded, since the stain intensity of SOX2 was obviously decreased in the shRNA-SOX2 group." (PMID 22615765, 2012). "The highest rate of lymph node- and distant metastases could be obtained in the group of CC with combined scores of high SOX2 and high β-catenin expression, whereas tumours with low or absent expression of both markers were associated with a reduced risk for loco-regional- and distant spread." (PMID 22168803, 2011).